NCAPD2 (non-SMC condensin I complex subunit D2)
Diseases named in the same sentence as NCAPD2 in open-access papers (continued):
Sharing a sentence is not in itself a finding about the gene and the disease.
cancer (18 papers, 2015 to 2025). A tumor composed of atypical neoplastic, often pleomorphic cells that invade other tissues. "While NCAPD2 has been implicated in promoting tumorigenesis across various cancer types, its specific role in LUAD remains underexplored." (PMID 41319185, 2025). "Among these subunits, NCAPD2, a component of condensin I, has recently been implicated in several cancers." (PMID 41319185, 2025). "NCAPD2 gene expression was significantly higher in most cancers and associated with clinical stage and poor prognosis." (PMID 38172945, 2024). "Our studies showed that NCAPD2 expression had significant positive associations with TMB in most cancers." (PMID 38172945, 2024). "We investigated differences in the expression levels of NCAPD2 and determined their association with clinical features, as well as their diagnostic and prognostic value using the cancer genome atlas database." (PMID 36701707, 2023). "In this study, NCAPD2 was found to be positively linked with TMB in nine types of cancer and negatively correlated with TMB in three types of cancer." (PMID 37498296, 2023). "We used the TIMER database to investigate the association between NCAPD2 expression and six immune cells from 33 cancers." (PMID 37498296, 2023). "The AUC of NCAPD2 in 20 types of cancer was > 0.8, indicating that NCAPD2 had high diagnostic accuracy in distinguishing cancer from normal tissues." (PMID 37498296, 2023). "The ROC of NCAPD2 was above 0.8 in 20 types of cancer, indicating a better diagnostic ability to distinguish between tumor tissue and normal tissue." (PMID 37498296, 2023). "It was found that NCAPD2 was overexpressed in pan-cancers, which was associated with poor outcomes." (PMID 38172945, 2024). "NCAPD2 was associated with one or more immune cell infiltrations in other cancers." (PMID 37498296, 2023). "Moreover, we generated ROC curves to evaluate the diagnostic efficacy of NCAPD2 in pan-cancer and normal samples." (PMID 37498296, 2023). "Then, we discovered the mRNA expression of NCAPD2 was higher in various cancer types, including DLBC, LGG, OV, SARC, TGCT and THYM (all P < 0.05)." (PMID 38172945, 2024). "Given the widespread implication of NCAPD2 in various cancers, it emerges as a promising therapeutic target in the realm of cancer treatment." (PMID 39220139, 2024). "NCAPD2-interacted proteins and NCAPD2 similar genes in pan-cancer were integrated, and three common genes were obtained." (PMID 38172945, 2024). "NCAPG, NCAPH and ASPM have strong positive correlations with NCAPD2 expression in different cancers, especially in THYM." (PMID 38172945, 2024). "Multiple online databases were analyzed NCAPD2 gene expression, protein level, patient survival and functional enrichment in pan-cancer." (PMID 38172945, 2024). "In our study, we found that the mRNA expression level of NCAPD2 was significantly increased in most cancers except ACC, LAML and UCS." (PMID 38172945, 2024). "In this study, another essential finding was that the expression of NCAPD2 gene is related to stemness index in most cancers." (PMID 38172945, 2024). "The findings from these studies underscore a potential general pro-oncogenic effect of NCAPD2, transcending the confines of specific cancer types." (PMID 39220139, 2024). "While the different contribution of NCAPD2 to chromosome in mitosis have been thoroughly investigated, much less is known about the expression of NCAPD2 in pan-cancer." (PMID 38172945, 2024). "Consistently, NCAPD2 expression had a significantly positive correlation with HRD score in most cancers, which evaluated as predictors of response to neoadjuvant platinum-based therapy." (PMID 38172945, 2024). "Our studies showed that NCAPD2 has frequent alteration in pan-cancer, and amplification as the most commonly occurring type of alteration, whereas structural variant was the rarest." (PMID 38172945, 2024).
cancer (continued). "In this study, we employed multiple databases and pan-cancer analyses to study the function of NCAPD2 in the prognosis and immunity of multiple tumors." (PMID 37498296, 2023). "Kaplan-Meier survival and univariate regression analyses were performed to explore the pan-cancer clinical significance of NCAPD2." (PMID 37498296, 2023). "NCAPD2 expression was positively correlated with the expression of RNA methylation-regulated genes in most cancers." (PMID 37498296, 2023). "Our results showed that NCAPD2 expression was positively correlated with the expression of RNA methylation-regulated genes in the majority of cancers." (PMID 37498296, 2023). "The biomarker evaluation and AUC of NCAPD2 in response to immunotherapy in cancer using TIDE database." (PMID 37498296, 2023). "Previous studies on NCAPD2 are limited to certain types of tumors, and pan-cancer NCAPD2 expression and correlation analysis have rarely been discussed." (PMID 37498296, 2023). "In our study, the overexpression of NCAPD2 in the vast majority of cancers was confirmed by TCGA and GTEx databases." (PMID 37498296, 2023). "Bioinformatic analysis showed that NCAPD2 was overexpressed in most tumors and correlated with the clinical characteristics of some cancers." (PMID 37498296, 2023). "Initially, TIMER 2.0 was used to assess the expression of NCAPD2 in diverse malignant tumors." (PMID 39220139, 2024). "We observed a positive correlation between NCAPD2 and cancer stemness: DNAss and RNAss." (PMID 38172945, 2024). "Furthermore, exploring the potential synergistic effects of combining NCAPD2 targeting with immunotherapy holds considerable promise for advancing cancer therapy." (PMID 39220139, 2024). "Therefore, our research provided insights into the application of NCAPD2 as pan-cancer prognostic markers." (PMID 38172945, 2024). "Moreover, topotecan (a topoisomerase I inhibitor) was highly drug sensitive in NCAPD2-overexpression cancer cells in this study." (PMID 38172945, 2024). "Downregulation of NCAPD2 can inhibit tumor growth in vivo, promote the release of pro-inflammatory factors, enhance cell cycle progression and invasive capabilities, regulate autophagy, and serve as a prognostic biomarker in various cancers." (PMID 39558952, 2024). "Here, we investigate the expression of NCAPD2 in a variety of cancers and its impact on the survival of patients with different cancers, and analyze the biological processes it may be involved in." (PMID 38172945, 2024). "Thus, we used a bioinformatics dataset to conduct a pan-cancer analysis of NCAPD2 to determine its regulatory role in tumors." (PMID 38172945, 2024). "In conclusion, our comprehensive first evaluated the role of NCAPD2 expression in the pan-cancer." (PMID 38172945, 2024). "The results presented here may provide new perspectives for the investigation of NCAPD2 as a potential cancer target." (PMID 38172945, 2024). "Therefore, we conducted a pan-cancer analysis of NCAPD2 gene expression, survival status, immune activity, DNA methylation, RNA methylation, and related cellular pathways based on multiple public databases." (PMID 37498296, 2023). "In addition, NCAPD2 was significantly linked with TME, immune checkpoints, TMB, MSI, DNA methylation, and RNA methylation in a variety of tumors, which contributed to the understanding of the latent role of NCAPD2 in human cancers from multiple viewpoints." (PMID 37498296, 2023). "Non-SMC condensin I complex subunit D2 (NCAPD2) is overexpressed in some malignant tumors." (PMID 37498296, 2023). "We selected OS, and DSS to investigate the prognostic value of NCAPD2 in different cancers." (PMID 37498296, 2023). "Finally, a recent HotNet2 Pan-Cancer analysis suggested that multiple cancers harbor rare mutations in SMC2, SMC4, NCAPD2, NCAPD3, NCAPH2 and NCAPG2, supporting a tumor-suppressor role for condensin proteins." (PMID 36169232, 2022).
cancer (continued). "Similarly, our studies indicated that NCAPD2 may regulate the tumor progression by mediating DNA repair and DNA methylation across cancers." (PMID 38172945, 2024). "Moreover, GSCA and GEPIA2 database showed that the expression of NCAPD2 was related to the stage of the certain cancers, and the expression level of NCAPD2 in LUAD, ACC, KIRP, BRCA, KIRC, ESCA and TGCT showed a gradual upward trend with the increase of clinical and pathological stage." (PMID 38172945, 2024). "Therefore, we investigated the crucial role of NCAPD2 in cancer initiation and progression." (PMID 37498296, 2023). "This may explain the overexpression of NCAPD2 in various cancers." (PMID 37498296, 2023). "NCAPD2 may act as a prognostic molecular marker in most cancers." (PMID 37498296, 2023). "However, there are few studies on the function of NCAPD2 in pan-cancer." (PMID 37498296, 2023). "Furthermore, we evaluated the effect of NCAPD2 expression on the prognosis of cancer patients." (PMID 37498296, 2023). "However, the role of NCAPD2 in cancer is poorly understood, and further analysis is needed." (PMID 31892156, 2019). "Our data link the condensin I subunit NCAPD2 to PI3K/AKT signaling, thereby connecting chromatin structural proteins with canonical cancer pathways." (PMID 41319185, 2025). "One-point worth noting was that the expression level of NCAPD2 was positively correlated with clinical stage and shorter survival (OS and DFS) in most cancer patients." (PMID 38172945, 2024). "Therefore, NCAPD2 may be a promising biomarker for immunological therapy in certain cancers." (PMID 37498296, 2023). "Therefore, targeting NCAPD2 may be a promising strategy for cancer treatment." (PMID 37498296, 2023). "We used the Cancer Genome Atlas (TCGA), Genotype-Tissue Expression (GTEx), Human Protein Atlas (HPA), and UALCAN to analyze NCAPD2 expression and promoter methylation levels in 33 tumors and normal samples." (PMID 37498296, 2023). "Using publicly available patient derived datasets obtained from TCGA, we determined that all eight condensin genes (SMC2, SMC4, NCAPD2, NCAPD3, NCAPG, NCAPG2, NCAPH, and NCAPH2) are frequently altered in at least 12 common cancer types." (PMID 31357676, 2019). "The condensin complex has been suggested as a potential therapeutic target for cancer, and human homologs YCG1/NCAPG2, YCS4/NCAPD2, and SMC4/SMC4 are synthetic lethal with the Ras oncogene." (PMID 31660150, 2019). "This study focused on non-SMC condensin I complex subunit D2 (NCAPD2) and investigated its effect on the pathogenesis and development of different tumors using pan-cancer analysis." (PMID 37498296, 2023). "We downloaded the NCAPD2 expression profile data of 33 cancers and corresponding normal tissue samples from TCGA and GTEx." (PMID 37498296, 2023). "In the ERBB2 network, we also found a subnetwork of direct protein–protein interactions formed by the non-SMC condensin I complexes (NCAPD2, NCAPG, NCAPH), a vital complex associated with the ERBB2 signaling pathway and cancer development." (PMID 33424936, 2020).
tumor (13 papers, 2012 to 2025). "In HCC, NCAPD2 not only acted as a hub gene, but also had diagnostic value in tumor tissues." (PMID 38172945, 2024). "NCAPD2 has been linked to the T stage, N stage, and tumor stage." (PMID 36701707, 2023). "Luc-PC9 stable control cells and NCAPD2 knockdown cells, both labeled with luciferase, were injected, and tumor growth was monitored biweekly using live animal imaging." (PMID 41319185, 2025). "In summary, in vivo xenograft assays confirmed that silencing NCAPD2 markedly reduced tumor growth and proliferation, which was consistent with the in vitro findings." (PMID 41319185, 2025). "In conclusion, this study illustrated the role of NCAPD2 in LUAD prognosis and provided experimental evidence that NCAPD2 promotes tumor development." (PMID 39220139, 2024). "Utilizing bioinformatics methodologies, we explored the differential expression of NCAPD2 between normal and tumor samples, along with its correlations with clinical-pathological characteristics, survival prognosis, and immune infiltration." (PMID 39220139, 2024). "In contrast to that in normal tissues, the TCGA-LUAD dataset revealed a notable increase in NCAPD2 expression in tumor tissues (p < 0.001)." (PMID 39220139, 2024). "In the TCGA-LUAD dataset, tumor samples demonstrated significantly elevated levels of NCAPD2 expression compared to normal samples (p < 0.001)." (PMID 39220139, 2024). "Compared with normal somatic copy number alterations (SCNA), the tumor infiltration levels were higher in DCs with different SCNA of NCAPD2 in LUAD and LUSC, and arm level gain frequently occurred in most TIICs (P < 0.05)." (PMID 38172945, 2024). "Subsequently, we found that NCAPD2 gene expression was related with the mark score of tumor heterogeneity, contains MSI, ploidy, MATH and LOH." (PMID 38172945, 2024). "Additionally, H&E and Ki67 staining were performed on sections of the fixed tumor tissue, revealing a lower Ki67-positive rate in tumors formed by NCAPD2 knockdown PC9 cells than in the control group." (PMID 41319185, 2025). "The effect of NCAPD2 on EMT was further evaluated in the context of tumor metastasis." (PMID 39220139, 2024). "Genetic alteration and tumor stemness of NCAPD2 were analyzed using cBioPortal and SangerBox." (PMID 38172945, 2024). "NCAPD2, located on chromosome 12, regulates the structure and separation of chromosomes and heterochromatin recombination, affecting cellular function abnormalities and playing a role in tumor development." (PMID 39558952, 2024). "Finally, we performed qPCR to verify differences in NCAPD2 expression between the tumor and normal tissues." (PMID 36701707, 2023). "In OV and THCA, NCAPD2 expression decreased with tumor progression." (PMID 37498296, 2023). "NCAPD2 plays a pivotal role in the occurrence and development of tumors and non-tumorous diseases." (PMID 37498296, 2023). "NCAPD2 is a tumor promoter that may be found in both in vitro and in vivo settings." (PMID 39403142, 2024). "Furthermore, the CIBERSORT results indicated a positive correlation between NCAPD2 expression and the 5 subtypes of Tumor-infiltrating immune cells (TIICs), including T cells CD4 memory activated, NK cells resting, Macrophages M0, Macrophages M1, and Mast cells activated." (PMID 36701707, 2023). "Therefore, NCAPD2 can be used as a biomarker to predict immunotherapy response for a certain tumor." (PMID 37498296, 2023). "NCAPD2 overexpression promoted LUAD cell proliferation and metastasis, while its knockdown inhibited tumor growth and invasion." (PMID 41319185, 2025). "The high NCAPD2 expression group had a lower ESTIMATE score, immune score, and Stromal score, but higher tumor purity." (PMID 36701707, 2023). "First, although we validated NCAPD2 function in multiple LUAD cell lines and xenograft models, we did not include patient-derived xenografts (PDXs) or organoid models, which better capture tumor heterogeneity." (PMID 41319185, 2025).
tumor (continued). "Since TIMER1 does not currently include normal tissues, we analyzed the NCAPD2 mRNA expression of other tumor tissues in GEPIA2 database instead." (PMID 38172945, 2024). "Herein, we confirmed the transcription levels of non-SMC subunit NCAPD3, NCAPH2, and NCAPD2 exhibited an increase in tumor tissues compared to adjacent nontumor tissues by RNA-seq analysis, among which only NCAPD3 showed a statistically significant change." (PMID 38561330, 2024). "Thus, NCAPD2 expression affected the TMB and MSI of tumors, thereby influencing the outcome of tumor immunotherapy." (PMID 37498296, 2023). "In LUAD and LUSC, NCAPD2 expression was not only positively correlated with CD4 + T cells, but also Th2 cells, which may imply that the ratio of Th1 cells to Th2 cells in CD4 + T cells is unbalanced, thus promoting tumor growth." (PMID 38172945, 2024).
NCAPD2 also shares sentences with these, for which no sentence is quoted: lung squamous cell carcinoma (3 papers); colon cancer (2); prostate carcinoma (2); adrenocortical carcinoma (1); autism (1); bile duct cancer (1); bladder cancer (1); cervical squamous cell carcinoma (1); colon adenocarcinoma (1); endometrial cancer (1); esophageal cancer (1); Fibrous Histiocytoma (1); glioblastoma (1); glioma (1); head and neck squamous cell carcinoma (1); hepatocellular carcinoma (1); leukemia (1); mesothelioma (1); minimal change disease (1); myxofibrosarcoma (1); neurodegenerative disease (1); pancreatic adenocarcinoma (1); pleomorphic liposarcoma (1); rectal adenocarcinoma (1); renal papillary cell carcinoma (1); skin cutaneous melanoma (1); thyroid cancer (1); uterine corpus endometrial carcinoma (1).